E2F1 (E2F transcription factor 1)
Description:
Transcription activator that binds DNA cooperatively with DP proteins through the E2 recognition site, 5'-TTTC[CG]CGC-3' found in the promoter region of a number of genes whose products are involved in cell cycle regulation or in DNA replication. The DRTF1/E2F complex functions in the control of cell-cycle progression from G1 to S phase. E2F1 binds preferentially RB1 in a cell-cycle dependent manner. Blocks adipocyte differentiation by binding to specific promoters repressing CEBPA binding to its target gene promoters. Directly activates transcription of PEG10. Positively regulates transcription of RRP1B.
Synonyms: E2F-1; RBBP3; RBP3; RBAP1
Tractability: Small molecule: a structure with a bound ligand is known. PROTAC: UniProt records ubiquitination sites on it; ubiquitination databases record sites on it. Other modalities: a drug acting on it is in phase 2 or 3 trials.
Target class: Transcription factor
Gene: Protein-coding gene on chromosome 20 (33,675,477 to 33,686,385, reverse strand). Ensembl gene ENSG00000101412.
Subcellular location: Nucleus
Subcellular location (Human Protein Atlas): Nucleoplasm; Centrosome
Pathways (Reactome):
Cell Cycle: Cyclin A:Cdk2-associated events at S phase entry; Cyclin D associated events in G1; Cyclin E associated events during G1/S transition; G1/S-Specific Transcription; G2 Phase; Inhibition of replication initiation of damaged DNA by RB1/E2F1; Transcription of E2F targets under negative control by DREAM complex; Transcription of E2F targets under negative control by p107 (RBL1) and p130 (RBL2) in complex with HDAC1
Cellular responses to stimuli: Oncogene Induced Senescence; Oxidative Stress Induced Senescence
Gene expression (Transcription): Transcriptional Regulation by E2F6
Programmed Cell Death: Activation of NOXA and translocation to mitochondria; Activation of PUMA and translocation to mitochondria
Developmental Biology: Transcriptional regulation of granulopoiesis
Disease: Defective binding of RB1 mutants to E2F1,(E2F2, E2F3)
Signal Transduction: Pre-NOTCH Transcription and Translation
Gene Ontology:
Molecular function: cis-regulatory region sequence-specific DNA binding; DNA binding; DNA-binding transcription activator activity; DNA-binding transcription activator activity, RNA polymerase II-specific; DNA-binding transcription factor activity; DNA-binding transcription factor activity, RNA polymerase II-specific; DNA-binding transcription factor binding; molecular adaptor activity; protein binding; sequence-specific DNA binding; sequence-specific double-stranded DNA binding; RNA polymerase II cis-regulatory region sequence-specific DNA binding; protein dimerization activity; protein kinase binding; transcription cis-regulatory region binding
Biological process: DNA damage checkpoint signaling; intrinsic apoptotic signaling pathway in response to DNA damage; mRNA stabilization; negative regulation of DNA binding; negative regulation of DNA-templated transcription; negative regulation of transcription by RNA polymerase II; positive regulation of apoptotic process; positive regulation of DNA-templated transcription; positive regulation of fibroblast proliferation; positive regulation of gene expression; positive regulation of transcription by RNA polymerase II; regulation of DNA-templated transcription; regulation of G1/S transition of mitotic cell cycle; DNA-templated transcription; negative regulation of fat cell differentiation; negative regulation of fat cell proliferation; regulation of transcription by RNA polymerase II; cellular response to fatty acid; cellular response to hypoxia; cellular response to nerve growth factor stimulus; positive regulation of glial cell proliferation; response to lipopolysaccharide; spermatogenesis
Cellular component: chromatin; nucleoplasm; nucleus; protein-containing complex; Rb-E2F complex; RNA polymerase II transcription regulator complex; cytoplasm; nuclear chromosome; transcription regulator complex
Genetic constraint (gnomAD): Loss-of-function variants: 7 observed, 32.95 expected, observed/expected ratio (o/e) 0.21, 90% interval 0.12 to 0.4. The upper end of that interval is the gene's LOEUF score, 0.4, which puts it in group 1 of 6, group 1 being the genes least tolerant of losing a copy. Missense variants: 406 observed, 523.32 expected, observed/expected ratio (o/e) 0.78, 90% interval 0.71 to 0.84. Synonymous variants: 261 observed, 241.24 expected, observed/expected ratio (o/e) 1.08, 90% interval 0.98 to 1.2.
Homologues: Orthologues: chimpanzee E2F1 (99% identical), macaque E2F1 (99% identical), dog E2F1 (92% identical), pig E2F1 (92% identical), rat E2f1 (86% identical), mouse E2f1 (84% identical), guinea pig E2F1 (73% identical), tropical clawed frog e2f1 (47% identical), zebrafish e2f1 (46% identical), Caenorhabditis elegans efl-3 (19% identical). Paralogues in human: E2F3 (40% identical), E2F2 (38% identical), E2F4 (26% identical), E2F5 (23% identical), E2F6 (22% identical), E2F7 (19% identical), E2F8 (18% identical).
Diseases named in the same sentence as E2F1 in open-access papers:
E2F1 is named in the same sentence as 326 diseases in open-access papers, as found by Europe PMC text mining. Sharing a sentence is not in itself a finding about the gene and the disease. The quoted sentences say what the papers report.
breast carcinoma (339 papers, 2004 to 2026). "CDK2, PCNA, CXCL8, and E2F1 were involved in the cell cycle, and were associated with worse survival for breast cancer." (PMID 40697521, 2025). "High E2F1 expression in breast cancer tissues is linked to poor prognosis, promoting tumor cell viability, metastasis, and cell cycle progression 43-45." (PMID 41281757, 2025). "E2F1 was directly implicated with poor prognosis in types of cancer, such as bladder cancer, breast cancer, ovarian cancer, prostate cancer, and has been demonstrated to be a key cancer biomarker." (PMID 37277745, 2023). "Using a computational pipeline, we used the map to unravel a tumor type-specific regulatory core and to predict receptor protein signatures in bladder and breast cancer underlying E2F1-mediated EMT transition." (PMID 37993971, 2023). "The interaction of FOXA1 with co-factors such as ESR1 and E2F1 enhanced the susceptibility of breast cancer." (PMID 36292640, 2022). "We observed that the top five strongest TF co-occupancy pairs associated with breast cancer risk were FOXA1 + E2F1, FOXA1 + NR2F2, FOXA1 + ESR1, FOXA1 + SIN3, and FOXA1 + TCF12." (PMID 34518541, 2021). "Based on large body evidence regarding the role of CNV in disease susceptibility and the altered expression of E2F1 in breast cancer, we have analysed CNVs of E2F1 in a cohort of 222 women with breast cancer." (PMID 33691613, 2021). "In MCF7 cells, L1 transposons were found to be bound by a total of 99 TFs, including ESR1, MYC, FOXA1 and E2F1, which have well-established and critical roles in cell growth and division and have been linked to breast cancer development." (PMID 34070697, 2021). "We find that, by analyzing genetic variations of TF-DNA bindings, the interaction of FOXA1 with co-factors such as ESR1 and E2F1, and the interaction of TFs with chromatin features (i.e., enhancers) play a key role in breast cancer susceptibility." (PMID 34518541, 2021). "LINC00511 has been implicated in breast cancer tumorigenesis and stemness through modulation of the miR-185-3p/E2F1/NANOG axis." (PMID 32244924, 2020). "This would allow us to identify E2F1 target genes which were previously implicated in breast cancer metastasis but would also allow to identify novel metastasis driver genes." (PMID 31341204, 2019). "The observed phenotype of increased DNA replication stress and accumulation of DNA damage upon Chk1 inhibition in Rb‐deficient breast cancer cell lines closely resembles the DNA replication catastrophe mediated by cyclin F loss and E2F1 deregulation." (PMID 31424118, 2019). "We analysed genome-wide binding sites for three breast cancer-associated TFs (C/EBPβ, E2F1 and MYC) in MCF7 cells, and confirmed that a substantial fraction of these TFBSs resided in TEs." (PMID 31061680, 2019). "In the present study, we attempted to investigate an association between the clinical data and E2F-1 expression in breast cancer." (PMID 31278126, 2019). "MiR-675 is already known to be derived from H19 and has been shown to be implicated in the development of colorectal and breast cancers, while both miR-203a and H19 have been shown to interact with E2F Transcription factor 1 (E2F1)." (PMID 30557328, 2018). "Herein, we demonstrated that E2F1 suppression by autophagy induction is closely associated with leptin-induced cell cycle progression in breast cancer cells." (PMID 29312618, 2017). "Consecutively, other researches have illustrated that lncRNA H19 was actively associated with the E2F1 (E2F transcription factor 1) to promote the cell-cycle progression of breast cancer cells." (PMID 27911863, 2017). "Consistent with our observation that overexpression of miR-106b and miR-93 predict sensitivity to CHOP, E2F1 expression has previously been associated with poor survival of breast cancer patients treated with FEC." (PMID 25692889, 2015). "Upregulated Bim expression in prostate and breast cancer cells was dependent on E2F1, where E2F1 silencing led to loss of Bim." (PMID 26405162, 2015).
breast carcinoma (continued). "In breast cancer, E2F1 has been implicated in tumour progression through oestrogen dependent as well as independent mechanisms." (PMID 26698305, 2015). "Our study identified epigenetic-mediated DNMT1 transcriptional repression, which involved the hypermethylated E2F1 motif-mediated loss of active histone modification H3K9ac and transcription factor E2F1 enrichment in BRCA1-mutated breast cancer." (PMID 24502362, 2014). "After the deletion of H3K9ac and/or E2F1 enrichment in BRCA1-mutated breast cancer, the transcription of DNMT1 was significantly down-regulated." (PMID 24502362, 2014). "Hypermethylated E2F transcription factor 1 (E2F1) motif is a key regulatory element for the DNMT1 gene in BRCA1-mutated breast cancer." (PMID 24502362, 2014). "High E2F1 expression is found in breast cancer tissues and is associated with a poor prognosis." (PMID 35293275, 2022). "Our findings suggest that copy number variations of E2F1 might be a susceptibility factor for breast cancer, however, further studies on large cohorts are to be performed in order to better delineate the phenotype linked to the gain of E2F1 copies." (PMID 33691613, 2021). "Regarding FOXM1, this transcription factor is a master regulator in cancer that is regulated by E2F1, and its overexpression is associated with an increased stem-like cell population and invasiveness in breast cancer, which is consistent with the C2 class being more dedifferentiated." (PMID 33396205, 2020). "In line with this, we have identified a suite of E2F1 target genes which have been previously implicated in breast cancer metastasis, suggesting that E2F1 may be a master regulator of breast cancer metastasis." (PMID 31341204, 2019). "While E2F1 is well known to regulate cell cycle and tumor progression, E2F1 may also mediate basal-like features as loss of E2F1 reduced squamous tumor incidence; importantly, squamous tumors show similarities to human basal-like breast cancer." (PMID 30484104, 2019). "Hence, RB1 loss, a common event in breast cancer, results in increased mRNA levels of E2F1 target genes." (PMID 28977935, 2017). "E2F1 was found to be associated with phenomena of resistance of targeted therapy in breast cancer." (PMID 28359318, 2017). "Our results demonstrate that KDM2A associated with Rb and E2F1 in a cell cycle dependent manner in breast cancer cells indicating that this interaction could probably be regulating cell cycle progression." (PMID 25029110, 2014). "Because tumor cell proliferation is linked to poor survival in breast cancer patients, we first tested whether the expression of the single "proliferation" gene, E2F1, was also linked to survival in breast cancer patients." (PMID 21453498, 2011). "In addition, we observed consistent gain of the E2F1 signature, which may be associated with metastatic progression of breast cancers." (PMID 35671075, 2022). "Because the expression of proliferation associated genes has been shown to group breast cancer patients into good and poor risk groups, we sought to identify genes whose expression could increase the predictive accuracy of the proliferation gene, E2F1." (PMID 21453498, 2011). "Previous studies have shown that the expression level of E2F1 can play a decisive role in the prognosis of breast cancer patients." (PMID 41394782, 2025). "Our results revealed an increase in the m6A-binding ability of YTHDF2, and the KD of YTHDF2 noticeably increased the stability and expression of c-Myc and E2F1 transcripts in breast cancer cells." (PMID 41281757, 2025). "This methylation influences gene expression by selectively recruiting the TF E2F1 to its target genes in breast cancer cells." (PMID 40809945, 2025). "For instance, E2F1-mediated ectopic expression of PP1A promotes breast cancer progression via activation of YAP1." (PMID 41050059, 2025).
breast carcinoma (continued). "Of note is the group of genes SP1, MYC, HEY2, E2F1, E2F2, and HES1, which are known to be associated with the KEGG breast cancer functional pathway." (PMID 40724805, 2025). "E2F1 exhibited higher expression levels in breast cancers compared to normal tissues, as well as in TNBC groups in comparison to non-TNBC groups." (PMID 41413688, 2025). "LncRNA DANCR promotes breast cancer cell proliferation, migration and invasion through the miR‐34c/E2F1 axis." (PMID 39951205, 2025). "Further multifactorial survival analysis showed that low expression levels of the c-Myc and E2F1 axis significantly improved OS in breast cancer patients." (PMID 41281757, 2025). "In sum, FTO and BTK are important regulators of c-Myc and E2F1 accumulation in breast cancer, and their induction of low expression levels is a major factor in improving the survival outcomes of breast cancer patients." (PMID 41281757, 2025). "Alizarin represented a promising approach to inhibit cell proliferation of breast cancer by modulating estrogen receptor mediated effects on MDM2/p-Rb/E2F1 axis concomitantly with activating apoptosis of cancer cells." (PMID 40580306, 2025). "Collectively, these findings highlight dual inhibition of FTO and BTK as a promising therapeutic strategy for maintaining low c-Myc and E2F1 expression levels, thereby improving survival outcomes and guiding future clinical management of breast cancer." (PMID 41281757, 2025). "This study also identified an upregulation of E2F1 in human breast cancer tissues compared to adjacent normal tissues." (PMID 38807590, 2024). "AGPG engaged in a physical interaction with PURα, which in turn freed E2F1 from PURα’s grasp, thereby triggering the activation of E2F1 signaling pathways in ERα-positive breast cancer cells." (PMID 39439957, 2024). "They observed that AURKA elevated the transcriptional activity of E2F1; while both proteins were found to be elevated in breast cancer tissues." (PMID 39598228, 2024). "ExomiR-205 can target E2F1 in vivo and in vitro to enhance tamoxifen resistance and proliferation in breast cancer." (PMID 38455764, 2024). "A notable negative correlation was observed between the mRNA levels of E2F1 and miR-372 in breast cancer tissues." (PMID 38807590, 2024). "Taken together, these data suggested that CDCA5 facilitated malignant behaviors of breast cancer cells via promoting the binding of E2F1 to FOXM1 promoter." (PMID 38978058, 2024). "Recently, it has been reported that RPL5 inhibits breast cancer cell growth by regulating ER stress and autophagy through E2F1 in breast cancer cells and tissues." (PMID 39684863, 2024). "MALAT1 played an essential role in breast cancer development by targeting miR-124/CDK4/E2F1 signaling pathway." (PMID 39119602, 2024). "The study also shows the E2F Transcription Factor 1 (E2F1) to be a direct target of ExomiR-205, in turn affecting the cellular transcription machinery in human breast cancer cells." (PMID 38455764, 2024). "PEPCK‐M promotes proliferation and cell cycle progression in ER+ breast cancer cells via upregulation of the mTORC1 and RB/E2F1 axes." (PMID 35757841, 2023). "For example, aloe emodin downregulates hTERT transcription in three breast cancer cell lines by upregulating E2F1 expression and downregulating c-MYC expression." (PMID 37612721, 2023). "Nuclear protein analysis revealed downregulation in the nuclear translocation of E2F1, which regulates centrosome amplification and metastasis in breast cancer." (PMID 36774386, 2023). "PEPCK‐M promotes proliferation and cell cycle progression in ER+ breast cancer via upregulation of the mTORC1 and E2F1 pathways." (PMID 35757841, 2023).